CHD2 (chromodomain helicase DNA binding protein 2)
Description:
ATP-dependent chromatin-remodeling factor that specifically binds to the promoter of target genes, leading to chromatin remodeling, possibly by promoting deposition of histone H3.3. Involved in myogenesis via interaction with MYOD1: binds to myogenic gene regulatory sequences and mediates incorporation of histone H3.3 prior to the onset of myogenic gene expression, promoting their expression (By similarity).
Synonyms: FLJ38614; DKFZp547I1315; DKFZp781D1727; DKFZp686E01200; DEE94; EEOC
Tractability: PROTAC: ubiquitination databases record sites on it; its protein half-life has been measured.
Gene: Protein-coding gene on chromosome 15 (92,886,203 to 93,027,996, forward strand). Ensembl gene ENSG00000173575.
Subcellular location: Nucleus
Subcellular location (Human Protein Atlas): Nucleoplasm; Golgi apparatus; Nucleoli; Vesicles
Pathways (Reactome):
Chromatin organization: CHD1 and CHD2 subfamily
Gene Ontology:
Molecular function: protein binding; RNA binding; ATP hydrolysis activity; ATP-dependent chromatin remodeler activity; chromatin binding; DNA binding; histone binding; RNA polymerase II cis-regulatory region sequence-specific DNA binding; ATP binding
Biological process: muscle organ development; nucleosome organization; chromatin remodeling; gene expression
Cellular component: chromatin; nucleoplasm; nucleus
Genetic constraint (gnomAD): Loss-of-function variants: 24 observed, 193.85 expected, observed/expected ratio (o/e) 0.12, 90% interval 0.089 to 0.17. The upper end of that interval is the gene's LOEUF score, 0.17, which puts it in group 1 of 6, group 1 being the genes least tolerant of losing a copy. Missense variants: 1,224 observed, 1,954.6 expected, observed/expected ratio (o/e) 0.63, 90% interval 0.6 to 0.66. Synonymous variants: 655 observed, 692.45 expected, observed/expected ratio (o/e) 0.95, 90% interval 0.89 to 1.01.
Gene-disease validity (ClinGen):
ClinGen rates the evidence that CHD2 causes each of these diseases.
complex neurodevelopmental disorder (autosomal dominant): Definitive. A disorder that involves more than one phenotype associated with the central nervous system, including but not limited to intellectual disability, autism, and seizures (epilepsy).
Homologues: Orthologues: chimpanzee CHD2 (99% identical), macaque CHD2 (99% identical), pig CHD2 (99% identical), mouse Chd2 (96% identical), rat Chd2 (96% identical), guinea pig CHD2 (90% identical), tropical clawed frog chd2 (79% identical), zebrafish chd2 (73% identical). Paralogues in human: CHD1 (58% identical), CHD5 (23% identical), CHD3 (22% identical), CHD9 (22% identical), CHD4 (22% identical), CHD7 (22% identical), CHD6 (21% identical), CHD8 (21% identical), SRCAP (20% identical), SMARCA4 (19% identical), SMARCA2 (19% identical), SMARCA1 (19% identical), and 18 more.
Diseases named in the same sentence as CHD2 in open-access papers:
CHD2 is named in the same sentence as 94 diseases in open-access papers, as found by Europe PMC text mining. Sharing a sentence is not in itself a finding about the gene and the disease. The quoted sentences say what the papers report.
epilepsy (50 papers, 2014 to 2026). A brain disorder characterized by episodes of abnormally increased neuronal discharge resulting in transient episodes of sensory or motor neurological dysfunction, or psychic dysfunction. "Mutations in the chromatin remodeler, CHD2, are strongly associated with moderate to severe intellectual disability, autism and epilepsy, but the direct contribution of CHD2 mutations to clinical phenotypes is poorly understood." (PMID 41872520, 2026). "Pathogenic variants in CHD2 are linked to early-onset conditions such as developmental and epileptic encephalopathy, drug-resistant epilepsies, and neurodevelopmental disorders." (PMID 39035822, 2024). "Mutations in the CHD2 gene can lead to neurodevelopmental delay, intellectual disability, epilepsy, and behavioural problems." (PMID 35386198, 2022). "In this report, we performed genetic analyses of the CHD2 gene in patients with epilepsy to identify new variants involved and to investigate the phenotypic spectrum associated with variants." (PMID 35627293, 2022). "Mutations in the CHD2 gene are inherited in an autosomal-dominant manner and can lead to intellectual disability, epilepsy, and autism." (PMID 35386198, 2022). "Individuals with CHD2 mutation exhibit a range of phenotypes and clinical diagnoses, including epilepsy, ASD, or both, as well as varying severity of clinical phenotypes." (PMID 36115870, 2022). "Among the various medications administered for treatment, valproate showed the best results for the treatment of epilepsy caused by CHD2 gene mutation." (PMID 35386198, 2022). "In this study, next-generation sequencing (NGS) was performed to identify likely pathogenic CHD2 variants in patients with epilepsy." (PMID 35627293, 2022). "Since photosensitivity is a common aspect of the epileptic phenotype in many CHD2 encephalopathy cases, the findings of these two Chd2 knockdown zebrafish studies strongly support the implication of de novo CHD2 mutations in epilepsy in humans." (PMID 33435571, 2021). "We do have a more complete picture for the ATP-dependent chromatin remodeler CHD2, which in humans is associated with epilepsy and broad-spectrum NDDs." (PMID 33263776, 2021). "The patients with mutations in CHD1/3/7/8 genes had epilepsy as a concomitant symptom of developmental abnormalities, while CHD2 mutations caused epileptic encephalopathy as a core phenotype." (PMID 34109749, 2021). "This manifests clinically: CHD2 disruption in human associates with epilepsy and mental deficiency or scoliosis." (PMID 31900031, 2020). "In a further case, a 24-year-old woman with childhood-onset migraine, aura and possible migralepsy was found to have a variant in a known epilepsy gene, the chromatin modifier CHD2 (c.2402C>G p.(Thr801Arg))." (PMID 31345272, 2019). "Overall, the vast majority (83%, 33/40) of patients carry truncating CHD2 variants, suggesting that the pathogenic mechanism that underpins CHD2-associated epilepsy is haploinsufficiency." (PMID 29962935, 2018). "Since then CHD2 pathogenic variants have been identified in a spectrum of patients with early-onset epilepsy." (PMID 29962935, 2018). "We show an enrichment of unique variants in CHD2 with photosensitivity in the common epilepsies overall, identifying CHD2 as a photosensitive epilepsy gene." (PMID 25783594, 2015). "As we continue to learn more about CHD2 mutations, the different epilepsy phenotypes, and photoparoxsymal responses associated with this gene, we will learn more about the pathophysiology and perhaps be able to develop new target treatments for epilepsy." (PMID 26933602, 2015). "The results of this study, in addition to our review of the literature, support a causative role of CHD2 haploinsufficiency in developmental delay, intellectual disability, epilepsy and behavioural problems, with phenotypic variability between individuals." (PMID 24834135, 2014). "A large number of studies demonstrated the phenotypic heterogeneity of CHD2-associated epilepsy." (PMID 35222528, 2022).
epilepsy (continued). "The pathogenesis of epilepsy caused by CHD2 is still unclear and may be related to decreased GABA activity." (PMID 35386198, 2022). "In this study, seven patients with epilepsy were treated with VPA to control their seizures, and it has been reported that VPA has good effect in the treatment of CHD2 mutation, but for patients with refractory epilepsy, a combination of medications or other methods are needed to control epilepsy." (PMID 35386198, 2022). "Patient 1, with a pathogenic CHD2-variant, c.1390A>T (p.Arg464*), had severe epilepsy in early age." (PMID 35979408, 2022). "Brain atrophy (patient 2) and incomplete penetrance (patient 3) could exist, and there might be a wider phenotype in epilepsy caused by CHD2 variants." (PMID 35627293, 2022). "The phenotypes caused by CHD2 variants can be highly variable except epilepsy." (PMID 35627293, 2022). "CHD2 mutations were also observed in patients with epilepsy." (PMID 34616726, 2021). "While this is the case, the mechanism by which epilepsy develops in patients affected by these mutations is still largely unknown, as is a comprehensive and definitive description of the role of CHD2, as distinct from the numerous extant related proteins." (PMID 33435571, 2021). "Unique CHD2 variants are also associated with photosensitivity in common epilepsies." (PMID 25783594, 2015). "We determined whether CHD2 variation underlies photosensitivity in common epilepsies, specific photosensitive epilepsies and individuals with photosensitivity without seizures." (PMID 25783594, 2015). "It has been predicted that the haploinsufficiency of CHD2 could cause epilepsies in children." (PMID 35627293, 2022). "Additional attention was drawn to CHD2 as a candidate photosensitive epilepsy gene as the only shared gene within several reported overlapping copy number variants of the chromosome 15q26.1 region associated with complex phenotypes including epilepsy with photosensitivity." (PMID 25783594, 2015). "CHD2, a chromatin remodeler linked to ASD, epilepsy, and intellectual disability, regulates gene expression through epigenetic mechanisms." (PMID 41833011, 2026). "CHD2-related epilepsy often manifests with diverse seizure types alongside developmental disabilities, autism, and photosensitivity." (PMID 39035822, 2024). "Although CHD2-related epilepsy is clinically well established, the molecular and functional mechanisms of CHD2 are continuously being investigated." (PMID 39035822, 2024). "More cases with detailed treatment histories were needed for the treatment and prognosis of CHD2-related epilepsy." (PMID 35627293, 2022). "Pathogenic mutation of CHD2 is known to contribute to NDDs, including ASD and epilepsy, while many ASD- and epilepsy-associated genes are likewise important for neural development and neuronal function." (PMID 36115870, 2022). "The genetic significance in PhS epilepsy was determined, in particular, by focusing on the CHD2 gene after finding it to be the only common gene among the few reported in PhS epilepsy with deletions in the chromosome 15q26.1 region." (PMID 35807051, 2022). "Mutations in the CHD2 gene (Chromodomain Helicase DNA Binding Protein 2), which encodes a member of the chromodomain helicase DNA-binding (CHD) family of proteins, have been identified in ASD, ID, and Epilepsy." (PMID 36061363, 2022). "We also systematically reviewed the published literature, provided a thorough overview of clinical, neuroimaging, physical, and genetic findings in CHD2-related epilepsy patients, and built the possible relationship between genotypes and phenotypes." (PMID 35222528, 2022). "Several CHD, such as CHD2, CHD6, CHD7, and CHD8, were found non-sense, heterozygous, or other kinds of mutations in patients with ASD, ID, and epilepsy." (PMID 34616726, 2021).
epilepsy (continued). "Several patients have been described with CHD2 deletions; with a common phenotype of intellectual disabilities, epilepsy and aggressive challenging behaviours." (PMID 29693535, 2018). "In comparison, fenfluramine also reduced ictal events, but the effect was less pronounced and not statistically significant, suggesting that ACZ’s effects may be specific to CHD2-related epilepsy." (PMID 40310132, 2025). "Variants detected in epilepsy-related genes (DEPDC5, CHD2, SCN8A and IQSEC2) have been reported in patients with SCN1A variants and were considered to contribute to blended phenotypes comprising features of the disorder associated with the epilepsy gene and Dravet syndrome." (PMID 38891831, 2024). "Additionally, there are also variants in genes related to epilepsy, such as CACNA1D (AUT142), CHD1 (AUT183), KMT2E (AUT184), and CHD2 (AUT195)." (PMID 38003033, 2023). "However, his ASD-affected brother carried the same deletion of the CHD2 gene, had similar dysmorphic features and mild ID, and experienced an epilepsy onset at 9 years of age." (PMID 35222528, 2022). "Up to now, most CHD2 variants have been reported de novo in patients with epilepsy rather than in an inherited mode." (PMID 35222528, 2022). "Therefore, a large sample size and follow-up studies would be helpful to define the treatment and prognosis of CHD2-related epilepsy." (PMID 35222528, 2022). "Indeed patients harbouring mutations in CHD2 present with a reduced head size and in 20% of the cases microcephaly, developmental delay, ID, ASD, epilepsy and behavioural problems with phenotypic variability between individuals." (PMID 33263776, 2021). "Another group of genes, CHD2, SCN10A, and TBC1D8, was associated with HGF and PTEN; these two genes are related to synaptic plasticity, neuronal cell survival, and CNS development, as well as related to epilepsy." (PMID 33584793, 2020). "Overall, these studies illustrate impaired inhibitory interneuron differentiation and migration are an important pathophysiological mechanism in epilepsy, including CHD2 haploinsufficiency, though further work is needed to understand pathophysiology at an electrophysiological level." (PMID 29962935, 2018). "To date, all disease-causing CHD2 variants in patients with epilepsy arise de novo, no transmission (i.e., autosomal dominant inheritance) has been observed, and one mutant allele is sufficient to cause disease." (PMID 29962935, 2018). "We also consider how CHD2 depletion can affect each of these biological mechanisms and how these defects may underpin neurodevelopmental disorders including epilepsy." (PMID 29962935, 2018). "Collectively, these results suggest impaired cortical excitatory cell development may be impaired with CHD2 and ARX loss, both genes implicated in early onset epilepsies, though further studies are required to understand the putative pathogenic role in development of seizures." (PMID 29962935, 2018). "CHD proteins play an important role in neurodevelopment, as pathogenic variants in CHD1, CHD2, CHD4, CHD7 and CHD8 have been associated with a range of neurological phenotypes, including autism spectrum disorder (ASD), intellectual disability (ID) and epilepsy." (PMID 29962935, 2018). "To investigate whether CHD2 may be associated with the broader phenotype of GGE rather than photosensitive epilepsies specifically, we tested whether rare variants in CHD2 were enriched in patients with GGE, with or without photoparoxysmal response." (PMID 25783594, 2015). "Disruption of Chd2 in mice causes embryonic death in some heterozygote pups and a complex phenotype including growth retardation and lordokyphosis: epilepsy has not yet been described." (PMID 25783594, 2015). "However, the exact mechanisms behind ACZ’s efficacy in CHD2-related epilepsy remain unclear." (PMID 40310132, 2025). "We therefore compared genes that were bound by CHD2 at each developmental time point in our experimental scheme with known ASD and epilepsy genes." (PMID 36115870, 2022).
epilepsy (continued). "The most common genes for epilepsy with genetic photosensitivity are SCN1A and CHD2, and the most common syndromes are PME and Dravet syndrome." (PMID 36034301, 2022). "Deletions affecting this gene are very rare, and, so far, there is only one case report of a child with global developmental delay, epilepsy and ASD who was found to have a de novo deletion encompassing the RGMA and CHD2 genes." (PMID 24834135, 2014). "Interestingly, a clinical case with moderate intellectual disability, epilepsy, and truncal obesity, suspected of PWS, showed a 15q26.1 microdeletion encompassing two genes: Chromodomain helicase DNA-binding protein 2 (CHD2) and RGMA." (PMID 39407757, 2024). "We referred to the mRNA sequences NM_001271.4 and protein sequences NP_001262.3 to analyze all the CHD2 non-CNVs related epilepsy patients." (PMID 35222528, 2022). "We compared CHD2 sequence data to publicly available data from 34 427 individuals, not enriched for epilepsy." (PMID 25783594, 2015). "The results of recent studies in which researchers used massively parallel sequencing in patient cohorts investigated for epilepsy, ASD or ID provide supporting evidence for a role of CHD2 haploinsufficiency in manifestation of the characteristics observed in our patients." (PMID 24834135, 2014). "In the case of patient E43, an 8-year-old boy exhibiting epilepsy characterized by atonic seizures, focal seizures, and permanent EEG changes since the age of 16 months, along with intellectual disability and microcephaly, we identified a deletion encompassing exons 2–28 of the CHD2 gene." (PMID 38328757, 2023). "So far, five patients carrying CHD2 CNVs but without epilepsy have been reported." (PMID 35222528, 2022). "Notably, 2 patients did not present with epilepsy, further supporting that epilepsy may not always be present in patients with CHD2 haploinsufficiency." (PMID 39035822, 2024). "Interestingly, patients without epilepsy tended to be CHD2 CNVs patients." (PMID 35222528, 2022). "Moreover, CHD2 knockdown in this inhibitory neuron model led to a reduced expression of genes involved in neurogenesis, synaptic transmission and genes involved in neurodevelopmental disorders, including epilepsy; upregulated genes were involved in cell adhesion and non-neural fate acquisition." (PMID 29962935, 2018).
Intellectual disability (17 papers, 2014 to 2026). "Four genes each were associated with human educational attainment and intellectual disability, of which CHD2, NRG3 and LRRC7 were associated with both." (PMID 36056154, 2022). "Sensitivity to generalized fever-induced seizures, as well as intellectual disability are common in individuals with mutations in either CHD2 or SCN1A." (PMID 33435571, 2021). "These mutations in the CHD2 gene are causative of early onset epileptic encephalopathy, abnormal brain function, and intellectual disability." (PMID 33435571, 2021). "Among them, HIVEP2 has been reported in patients characterized by developmental delay and intellectual disability, and CHD2 was found implicated in the development of selected neural circuits (i.e., cortical and hippocampal circuits) and long-term memory." (PMID 31652596, 2019). "For example, deletions of CHD2 were detected in patients affected by epilepsy and severe intellectual disability." (PMID 37190088, 2023). "In addition to CHD3, CHD4 and CHD5, other highly related members of the CHD superfamily, CHD2, CHD7 and CHD8 have also been implicated in ASD and intellectual disability." (PMID 37190088, 2023).